G6PD (glucose-6-phosphate dehydrogenase)
Diseases named in the same sentence as G6PD in open-access papers (continued):
Sharing a sentence is not in itself a finding about the gene and the disease.
malaria (continued). "Nearly all malaria-endemic countries in the Asia-Pacific region have committed to malaria elimination by 2030; however most of these countries do not test for G6PD deficiency on a routine basis and PQ is often not prescribed." (PMID 28797255, 2017). "Therefore, mandatory G6PD testing is the only option for Pakistan before intervening for malaria eradication with primaquine." (PMID 29065882, 2017). "Although the lessons learnt from the introduction of malaria RDTs are relevant to G6PD testing, the former are required for diagnosing an acute infection, whereas the latter are required for safety and prevention of future infections, and thus the experience and challenges are often different." (PMID 28381261, 2017). "Because these various polymorphisms are all in linkage disequilibrium with each other, the corresponding genetic effect might reflect haplotypes protecting from malaria, as demonstrated for the G6PD locus in a study from Tanzania." (PMID 28541483, 2017). "Knowing the G6PD status of patients might be beneficial not only in the context of malaria but also in the context of other infections such as typhoid fever, dengue infection and viral hepatitis." (PMID 29082022, 2017). "Other studies in Brazil have also reported an absence of association between G6PD phenotypes and the number of previous episodes of malaria." (PMID 28619120, 2017). "Due to the low number of G6PD deficient malaria patients detected in this study, it was not possible to examine in any detail the potential interaction between the forms of deficiency found and the severity of falciparum malaria or its form of illness." (PMID 28356147, 2017). "We observed absence of negative association between G6PD deficiency not only with uncomplicated falciparum malaria but also with severe malaria." (PMID 28382932, 2017). "Heterozygous females would have the greatest selective advantage since they would not suffer from favism or other G6PD associated outcomes while being protected against severe malaria." (PMID 28152025, 2017). "The differences in G6PD activity found in various Colombian studies are probably due to composition of the different populations evaluated; a higher G6PDd prevalence in Afro-descendants is likely, particularly in malaria endemic regions." (PMID 27225440, 2016). "From the 287 malaria children enrolled, the G6PD genotypes were available for only 278 children." (PMID 27388012, 2016). "Malaria patients should confirm their G6PD status before intake of anti-malarial drug." (PMID 27880809, 2016). "A single course of PQ significantly reduces gametocyte carriage in malaria-infected asymptomatic, G6PD-normal individuals without increasing the risk of clinical anemia." (PMID 27825738, 2016). "The CareStartTM G6PD RDT proved reliable as a point-of-care test to screen for severely G6PD-deficient patients and to make clinical decisions prior to primaquine administration in malaria elimination strategies." (PMID 27329471, 2016). "The aim of this study was to assess the efficacy of the recommended schizontocidal regimens and to measure the prevalence of G6PD deficiency and haematological consequences among non-severe G6PD deficient patients with malaria in the CHT of Bangladesh." (PMID 27128675, 2016). "Though part of former anthropological studies, G6PD genetic variation in French Guiana in relation with malaria risk has never been carried out so far." (PMID 27267757, 2016). "This may occur due to the greater number of new erythrocytes produced as a result of the acute haemolysis provoked by malaria, since new erythrocytes present more G6PD enzymatic activity when compared to mature cells, which may lead to false negative results." (PMID 26864333, 2016). "Moreover, the long-term stability and conserved performance of the CareStartTM G6PD RDT at high temperatures makes it appropriate for use in malaria-endemic areas in Yemen." (PMID 27329471, 2016).
malaria (continued). "Previous work in the same individuals using 68 SNPs across well-documented malaria candidate genes (eg, HbAS, G6PD, major histocompatibility complex class III loci) revealed only the HbAS polymorphism to be associated strongly with protection from all forms of severe malaria (P < 10−8)." (PMID 25805752, 2015). "We investigated the effect of G6PD deficiency on a range of malaria-specific and non-malaria outcomes in children living in an area in which the G6PD c.202T allele is the only significant genetic cause." (PMID 26686045, 2015). "Sub-Saharan Africa, with a relatively high but poorly characterized G6PD prevalence, could potentially benefit from the use of primaquine to further reduce or interrupt malaria transmission." (PMID 25887344, 2015). "Likewise, the scientific community failed to view safe access to primaquine therapy as a problem in need of solving, either by replacing primaquine or developing G6PD diagnostics suited to where most malaria patients live." (PMID 26652887, 2015). "These phenotype-genotype inconsistencies may be explained in part by variation in study design, G6PD and malaria phenotypic complexity and misclassification and incomplete experimental data." (PMID 25671784, 2015). "Recent efforts at elaborating a genetic architecture of malaria have focused on severe malaria, leading to the identification of two new genes and confirmation of previously known variants in HBB, ABO and G6PD, by exploring the whole human genome in genome-wide association (GWA) studies." (PMID 25887595, 2015). "The ability of national malaria control programs to adopt and integrate G6PD screening capacity into their healthcare delivery systems (to the very periphery) hinges upon the endorsement, encouragement and direct support of international agencies and civil societies." (PMID 26652887, 2015). "We suggest, therefore, that historically, malaria alone may be sufficient to explain balancing selection against G6PD c.202T hemizygous boys and homozygous girls." (PMID 26686045, 2015). "The G6PD RDT kit could be used to screen malaria patients before administration of the fixed dose primaquine with ACT as recommended by the WHO." (PMID 25885097, 2015). "In malaria endemic areas, the prevalence of G6PD ranges from 5.0% to 23.8%." (PMID 25885097, 2015). "Here we investigate associations between 68 SNPs within the G6PD and surrounding loci (IKBKG and CTAG1A/B), including the 202, 376, 542, 680 and 968 A- deficiency polymorphisms (referred to here as G6PD202, G6PD376, and so forth), and severe malaria." (PMID 25671784, 2015). "This outcome could be related to the accuracy of the specific G6PD laboratory test or the patient had in the past hemolytic anemia due to malaria relapse or for unknown reasons." (PMID 26583650, 2015). "We find very strong associations between multiple SNPs across the G6PD gene and protection from severe malaria in female heterozygotes but not in hemizygous males." (PMID 25671784, 2015). "At the time of sampling, national antimalarial treatment guidelines in Afghanistan recommended chloroquine as the first-line treatment of P. vivax (alongside a 14-day course of primaquine, where the G6PD status of the patient can be ascertained) as well as for cases of unconfirmed malaria." (PMID 25897070, 2015). "Higher G6PD prevalence rates appear more commonly where higher rates of malaria transmission occur." (PMID 26416229, 2015). "Obviously, most of the methods available and accepted for routine screening of G6PD status of patients are not suitable to be employed to screen for G6PD status of patients at point-of-care in malaria endemic regions in the tropics where screening for G6PD is most needed." (PMID 25885097, 2015). "The other malaria cases were G6PD normal including two falciparum malaria cases." (PMID 25541721, 2014).
malaria (continued). "The RBC is essential for the erythrocytic stage of malaria infection; consequentially human RBC traits, such as hemoglobinopathies, G6PD deficiency and differential expression of host RBC invasion ligands, have arisen in the human population providing protection from malaria." (PMID 24984000, 2014). "Various ethnic groups live in northwestern Thailand along the Myanmar border where malaria is endemic, and although G6PD deficiency is common, no phenotypic or molecular characterization of G6PD variants affecting this population has been performed." (PMID 25536053, 2014). "Among male children, the G6PD deficient children had higher odds of contracting malaria but this was not statistically significant (adjusted OR = 1.20, 95% CI: 0.53–2.71, p = 0.657)." (PMID 25470251, 2014). "It further provides the first evidence that polymorphisms in NOS2 and EMR1 may be associated with mild malaria, G6PD with anaemia while SNPs in ADCY9 and EMR1 may be linked with severe malaria in the Cameroonian population." (PMID 24934404, 2014). "In Brazil, an absence of association between G6PD phenotypes and the number of previous episodes of malaria in men was reported." (PMID 24568147, 2014). "Whilst there is strong evidence that G6PD A- deficiency is protective against severe malaria, the effect on mild forms of disease has not been demonstrated conclusively." (PMID 25015414, 2014). "Thus, mutant globins, glucose-6-phosphate dehydrogenase (G6PD), and Duffy antigen genes are paradigmatic examples of malaria protection." (PMID 24847360, 2014). "The significantly higher occurrence of malaria smear positivity among G6PD-deficient individuals, compared to the non-deficient, observed in this study suggests lack of correlation between G6PDd and protection from clinical malaria." (PMID 25406667, 2014). "Using 20 high-quality biallelic (of 68) G6PD SNPs, including the established G6PD202, 376, and 968 markers, allele frequencies between the Dogon and Fulani ethnic groups were compared, and tests of association with mild malaria phenotypes performed." (PMID 25015414, 2014). "The G6PD deficient children were 1.76 times more likely to contract malaria as compared to the G6PD normal subgroup, although this association was not significant (adjusted OR = 1.76, 95% CI: 0.98–3.16, p = 0.06)." (PMID 25470251, 2014). "This study consists of 939 subjects genotyped at 166 single nucleotide polymorphisms (SNPs) from genes involved in known malaria resistance (e.g. HBB, G6PD), cytokine production (e.g. TNF, LTA, IL1, 3, 4, 5, 7, 10, and 13), innate immunity (e.g. TLR 4,9) and the 5q31-33 region (117 SNPs)." (PMID 24098393, 2013). "In addition to the sickle polymorphism (HbS), G6PD, and ABO blood group, a number of candidate polymorphisms have been proposed for the reduced risk of severe malaria." (PMID 22957039, 2012). "In addition to the sickle polymorphism (HbS), G6PD, and ABO blood group, a number of other traits have been proposed for the reduced risk of severe malaria." (PMID 23144702, 2012). "G6PD-deficient subjects are prone to hemolysis induced by primaquine, an antimalarial drug used in this area without screening, further aggravating malaria-related anemia." (PMID 22574149, 2012). "Such variation maybe attributed to variable G6PD gene flow from Southern Europe and Africa, as well as on the presence of ethnic variations and the endemicity of malaria." (PMID 22452742, 2012). "The effects of polymorphisms in a number of genes, including β-globin, G6PD, TNF-α, IFN-γ, CD36, ICAM-1, IL10, IL4R, and LTA, upon the clearance of malaria parasites in African individuals was investigated across five large association studies from Burkina Faso, Cameroon, Kenya, Mali, and Sudan." (PMID 21867552, 2011).
malaria (continued). "Several RBC polymorphisms, including those linked to glucose-6-phosphate dehydrogenase, pyruvate kinase, complement receptor-1 and haemoglobinopathies, have a role in the clinical outcome of malaria, but were not included for analysis in the present study." (PMID 22011404, 2011). "Lastly, there were no clinical differences between G6PD-deficient and -normal patients with malaria enrolled into the CDA clinical trials." (PMID 21849081, 2011). "Effect of malaria, sex, age group, village, and tribe on frequency of phenotypic G6PD." (PMID 20520804, 2010). "Malaria transmission history and genotyping of the G6PD gene from this population may be able to shed light on this." (PMID 20684792, 2010). "We were not able to measure reticulocytes, but we did not detect any association between G6PD level and history of treatment for malaria within the two weeks preceding G6PD activity testing." (PMID 19789650, 2009). "Therefore, this study aimed to estimate the prevalence of G6PD in an endemic area for malaria in Manaus, in the Brazilian Amazon." (PMID 19370159, 2009). "High frequencies of host erythrocyte polymorphisms such as α+-thalassaemia, haemoglobin (Hb) S, Hb C, Hb E, complement receptor-1 (CR1) deficiency, glucose-6-phosphate dehydrogenase (G6PD) deficiency and south-east Asian ovalocytosis (SAO) are found in malaria endemic areas." (PMID 18173836, 2008). "In the subset of 529 children for whom there were data on Hb genotype and G6PD status, the protective effect against malaria and anaemia adjusted for the effect of age, bednet use, Hb type and G6PD status was statistically significant in the AS+AQ monthly group compared to the placebo group." (PMID 19098989, 2008). "Immediate scale-up of G6PD testing and radical cure for P. vivax, coupled with geographically targeted vector control in urban and highland hotspots, enhanced surveillance in highland and urban areas, and innovative measures against urban vectors, is essential to avert a regional malaria burden." (PMID 41286876, 2025). "This is crucial in remote communities, as a feasibility study of implementing new G6PD testing at health centres in 2021 suggested that only half of the eligible patients visited the health centres for G6PD testing after they were diagnosed with malaria by VMWs on the communities." (PMID 39661587, 2024). "However, future development of G6PD tests that are easier to interpret or more durable to withstand field conditions, may encourage CNM or other malaria programmes to conduct community level G6PD testing." (PMID 38395925, 2024). "Also, primaquine can trigger life-threatening hemolysis in individuals with glucose-6-phosphate dehydrogenase (G6PD)-deficiency, an X-linked enzymatic condition that is common in malaria-endemic settings, and in settings such as Thailand, is estimated to affect 13–17% of the population." (PMID 37438774, 2023). "Studies have shown that asymptomatic P. falciparum infection is common in the population, and G6PD deficient individuals may be carrying malaria parasites without symptoms." (PMID 38062464, 2023). "Malaria infection might impose selection for G6PD genetic mutation that results in higher prevalence of G6PDd in malaria endemic than non-endemic areas." (PMID 36076204, 2022). "Our findings raise the possibility that aparasitemic individuals identified as severely or intermediate G6PD deficient may not necessarily be at high risk of drug induced haemolysis during malaria." (PMID 35544453, 2022). "Therefore, although the national malaria treatment guidelines have recommended primaquine for the radical cure of P. v, they have also mandated that primaquine should only be administered with prior G6PD testing." (PMID 36264996, 2022). "Similarly, Individuals with previous history of Plasmodium infection were more likely to be G6PD deficient than those who were not previously infected with malaria (AOR = 4.0, 95% CI 1.2–12.7, p-value = 0.02)." (PMID 36076204, 2022).
malaria (continued). "However, the haematological parameters in malaria patients with G6PD and PKLRR41Q mutations have not been thoroughly investigated." (PMID 36038921, 2022). "However, none of the G6PD alleles correlated with low levels of glucose among the severe malaria patients." (PMID 35527254, 2022). "If these findings are confirmed, it raises the possibility that an individuals’ G6PD status is not static, and thus the risk of drug induced haemolysis when presenting with malaria cannot be assumed from measuring an individual’s enzyme activity when aparasitaemic." (PMID 35544453, 2022). "The proportion of G6PDd among malaria patients (16.7% by RDT, 14.9% usPCR) in this study in two national groups of the western part of Myanmar indicated G6PD testing or special interventions and/or alternative strategies may be required to achieve malaria elimination goal in Myanmar." (PMID 34108049, 2021). "This study provides new insights into the mechanism of G6pd deficiency mediated resistance against ECM and acute liver injury in the early stage by suppressing the host immune system induced by P.berghei parasites and provides an understanding of the malaria natural selection pressure." (PMID 34456927, 2021). "As the integration of POC G6PD testing represents a significant shift in malaria case management, malaria control programmes are eager for ways to certify and monitor user competency, and the concept of the usability assessment instrument may serve an important purpose to this end." (PMID 34238299, 2021). "The significant differences in these estimates may reflect study populations with different ethnic backgrounds, and associated differences in G6PD genetic profiles, or an underlying difference in G6PD activity in patients with and without malaria." (PMID 32925910, 2020). "In the GMS, the remaining malaria hotspots are mainly concentrated amongst hard-to-reach ethnic minorities and mobile migrant populations whose limited uptake of preventive measures and treatment presents an additional difficulty for the efficient roll-out of G6PD testing and radical cure." (PMID 33396538, 2020). "Thus, it is likely that the Chinese G6PD gene may have been strongly impacted by natural selection due to its protective effect against malaria." (PMID 33128437, 2020). "Finally, the G6PD RDT has temperature limitations similar to malaria RDTs." (PMID 32372747, 2020). "Knowing this cut-off value likely to result in haemolysis enables the treatment of some G6PD heterozygous women who would be likely to tolerate primaquine or tafenoquine therapy for malaria who otherwise might have been excluded because of their heterozygosity." (PMID 32552815, 2020). "This hypothesis is supported by studies demonstrating a negative association between G6PD A− variant and severe malaria, particularly in hemizygote deficient males and homozygote deficient females." (PMID 30819192, 2019). "Deficiency of glucose-6-phosphate dehydrogenase (G6PDd) and Duffy-negative blood group are two red blood cells variants that exhibit pattern of population distribution strongly influenced by natural selection by malaria." (PMID 30508000, 2018). "As most of the recipients of blood in our study population may usually be suffering from severe malaria and on drug therapy, this calls for some urgency in the inclusion of G6PD and/or HbS status in all prospective donors so as to protect the potential recipients." (PMID 27703480, 2016). "The CareStartTM G6PD RDT proved reliable as a point-of-care test to screen for severely G6PD-deficient patients, with 100 % sensitivity and NPV, and it can be used for making clinical decisions prior to the administration of primaquine in malaria elimination strategies." (PMID 27329471, 2016).